FIP1L1 (factor interacting with PAPOLA and CPSF1)
Description:
Component of the cleavage and polyadenylation specificity factor (CPSF) complex that plays a key role in pre-mRNA 3'-end formation, recognizing the AAUAAA signal sequence and interacting with poly(A) polymerase and other factors to bring about cleavage and poly(A) addition. FIP1L1 contributes to poly(A) site recognition and stimulates poly(A) addition. Binds to U-rich RNA sequence elements surrounding the poly(A) site. May act to tether poly(A) polymerase to the CPSF complex.
Synonyms: hFip1; FIP1; RHE; DKFZp586K0717
Tractability: PROTAC: ubiquitination databases record sites on it; its protein half-life has been measured.
Safety:
Unwanted effects reported when the protein is acted on. In parentheses: how it was acted on, where the effect was seen, and who reports it.
adverse events (source: ClinPGx)
Gene: Protein-coding gene on chromosome 4 (53,377,562 to 53,464,382, forward strand). Ensembl gene ENSG00000145216.
Subcellular location: Nucleus
Subcellular location (Human Protein Atlas): Nucleoplasm
Pathways (Reactome):
Metabolism of RNA: Processing of Intronless Pre-mRNAs; Transport of Mature mRNA Derived from an Intronless Transcript; mRNA 3'-end processing; mRNA Polyadenylation
Disease: Dengue Virus-Host Interactions; Signaling by cytosolic PDGFRA and PDGFRB fusion proteins
Gene expression (Transcription): RNA Polymerase II Transcription Termination
Gene Ontology:
Molecular function: protein binding; RNA binding
Biological process: mRNA 3'-end processing; mRNA 3'-end processing by stem-loop binding and cleavage
Cellular component: mRNA cleavage and polyadenylation specificity factor complex; nucleoplasm; cytosol; nucleus
Genetic constraint (gnomAD): Loss-of-function variants: 11 observed, 48.12 expected, observed/expected ratio (o/e) 0.23, 90% interval 0.14 to 0.38. The upper end of that interval is the gene's LOEUF score, 0.38, which puts it in group 1 of 6, group 1 being the genes least tolerant of losing a copy. Missense variants: 353 observed, 516.56 expected, observed/expected ratio (o/e) 0.68, 90% interval 0.63 to 0.75. Synonymous variants: 191 observed, 170.16 expected, observed/expected ratio (o/e) 1.12, 90% interval 1 to 1.27.
Homologues: Orthologues: chimpanzee FIP1L1 (100% identical), dog FIP1L1 (99% identical).
Diseases named in the same sentence as FIP1L1 in open-access papers:
FIP1L1 is named in the same sentence as 69 diseases in open-access papers, as found by Europe PMC text mining. Sharing a sentence is not in itself a finding about the gene and the disease. The quoted sentences say what the papers report.
eosinophilia (29 papers, 2009 to 2026). "Myeloproliferative neoplasm (MPN) with eosinophilia associated with FIP1L1-PDGFRA is a rare eosinophilic disorder typically treated with imatinib." (PMID 40141849, 2025). "In this report, we present a case of a patient with FIP1L1-PDGFRA T674I-positive MPN with eosinophilia, harboring a PTPN11 (p.E76D) mutation." (PMID 40141849, 2025). "Myeloproliferative neoplasm (MPN) with eosinophilia associated with FIP1L1-PDGFRA is a form of hypereosinophilic syndrome." (PMID 40141849, 2025). "While imatinib is highly effective for FIP1L1-PDGFRA-positive MPN with eosinophilia, the T674I mutation confers resistance, necessitating alternative approaches." (PMID 40141849, 2025). "This case highlights the formidable therapeutic challenges of FIP1L1-PDGFRA T674I-positive MPN with eosinophilia with concurrent PTPN11 (p.E76D) mutation." (PMID 40141849, 2025). "Treatment options for FIP1L1-PDGFRA-positive MPN with eosinophilia with T674I mutation remain challenging." (PMID 40141849, 2025). "The FIP1L1-PDGFRA fusion gene is the most frequent molecular abnormality seen in eosinophilia-associated myeloproliferative disorders, but is also present in acute myeloid leukemia (AML), T-lymphoblastic leukemia/lymphoma (TLL), or both simultaneously." (PMID 36517458, 2022). "This study was undertaken to learn the prevalence and associated clinicopathologic and genetic features of FIP1L1-PDGFRA rearrangement in a cohort of 26 adult patients presenting with profound eosinophilia (>1.5x109/L)." (PMID 24764730, 2014). "Myeloproliferative neoplasm with eosinophilia and platelet-derived growth factor receptor-alpha gene and Fip1-like 1 gene mutation (FIP1L1-PDGFRA; F/P) is a low-burden disease with dramatic response to imatinib therapy." (PMID 24764730, 2014). "This study was undertaken in order to examine the prevalence and the associated clinicopathologic and genetic features of FIP1L1-PDGFRA rearrangement in a cohort of 15 adult patients presenting with profound eosinophilia (> 1.5 × 109/L)." (PMID 19187542, 2009). "In this study we describe our experience for the diagnostic utility of the detection of FIP1L1-PDGFRA rearrangement in patients with profound eosinophilia." (PMID 19187542, 2009). "Moreover, recent studies showed if the eosinophilia-associated AML patients presented the FIP1L1-PDGFRA fusion gene, they should be as excellent candidates for treatment with tyrosine kinase inhibitors." (PMID 27903959, 2017). "This study was undertaken in order to examine both the prevalence and the associated clinicopathologic and genetic features of FIP1L1-PDGFRA rearrangement in a cohort of 15 adult patients presenting with eosinophilia and an absolute eosinophil count higher than 1.5 × 109/L." (PMID 19187542, 2009). "In the context of FIP1L1-PDGFRA-positive MPN with eosinophilia, the concurrent PTPN11 mutation could have amplified downstream signaling, making the leukemic cells less dependent on PDGFRA-driven pathways and more resistant to tyrosine kinase inhibitors like imatinib." (PMID 40141849, 2025). "According to recent data, the average yearly incidence of FIP1L1-PDGFRA-positive myeloid neoplasm with eosinophilia is 0.18 cases per one million people, with a predominance in males." (PMID 40141849, 2025). "When an elevated eosinophil count is identified, further workup, including molecular studies for clonal eosinophilia (e.g. testing for the FIP1L1-PDGFRA rearrangement), should be pursued to confirm the diagnosis." (PMID 40384954, 2025). "This case presents the first reported instance of concurrent FIP1L1-PDGFRA T674I and PTPN11 (p.E76D) mutations in a 38-year-old male patient with MPN and eosinophilia." (PMID 40141849, 2025). "Our patient had severe eosinophilia, thrombocytopenia, and thrombosis so we evaluated him for underlying primary HES by sending the FIP1L1–PDGFRA fusion gene, PDGFRB JAK2V617F mutation, CALR, and BCR‐ABL mutation." (PMID 35242558, 2022).
eosinophilia (continued). "The FIP1L1-PDGFRA gene fusion was detected by fluorescence in situ hybridization (FISH) on peripheral blood, diagnostic for myeloid/lymphoid neoplasm with eosinophilia." (PMID 36241191, 2022). "Bone marrow aspirate revealed dysplastic eosinophilia and a FIP1L1-PDGFRA fusion gene (4q12) was detected, confirming EL." (PMID 35722086, 2022). "FIP1L1-PDGFRα fusions: the FIP1L1-PDGFRα rearrangement represents the most frequently recurrent aberration in eosinophilia detected in different hematopoietic cells, including eosinophils, neutrophils, T-, or B-cells." (PMID 33418988, 2021). "All of the patients described had histories of peripheral eosinophilia, which prompted targeted testing for the FIP1L1-PDGFRA rearrangement, since this rearrangement is cryptic and cannot be detected by conventional karyotype." (PMID 26457233, 2015). "Amongst the 15 patients with eosinophilia, only two were positive for the FIP1L1-PDGFRA rearrangement (13,3%)." (PMID 19187542, 2009). "In the study, with the largest cohort, Pardanani and co-workers screened 741 patients with moderate to severe eosinophilia and reported a 3% prevalence of FIP1L1-PDGFRA fusion positivity." (PMID 19187542, 2009). "The patient was diagnosed with FIP1L1-PDGFRA-positive myeloid with eosinophilia." (PMID 40141849, 2025). "However, to date, only imatinib has been approved as a first-line treatment for patients with myeloid disease, with eosinophilia expressing FIP1L1-PDGFRα or carrying other PDGFRα or PDGFRβ fusions." (PMID 33418988, 2021). "However, in myeloproliferative disorders with eosinophilia, FIP1L1-PDGFRBA fusion has been observed." (PMID 32766158, 2020). "The identification of new onset of eosinophilia in acute myeloid leukemia arising in a patient with chronic myelomonocytic leukemia might indicate acquisition of imatinib-responsive FIP1L1-PDGFRA rearrangement." (PMID 24669761, 2014). "The last patient, suffering from systemic mastocytosis with eosinophilia, was negative to FIP1L1-PDGFRA rearrangement, as well as to the C-KIT-D816V mutation, but did not respond to imatinib treatment." (PMID 19187542, 2009). "It is obvious, that a subsequent meta-analysis, taking into account all published studies, could clarify the true prevalence of FIP1L1-PDGFRA rearrangement in patients with idiopathic eosinophilia and HES." (PMID 19187542, 2009). "Systemic eosinophilic disorders (e.g., HES, EGPA): Marked peripheral eosinophilia and multi-organ involvement guide diagnosis, often supported by laboratory testing (AEC, FIP1L1-PDGFRA)." (PMID 41007791, 2025). "We tested the FIP1L1/PDGFRA and BCR/ABL fusion genes to exclude the possibility of a myeloid neoplasm or clonal eosinophilia." (PMID 33916211, 2021). "Myeloid neoplasm with eosinophilia and FIP1-like-1-platelet-derived growth factor receptor-alpha (FIP1L1-PDGFRA) rearrangement is a multi-organ disease with diverse clinical presentation." (PMID 31737382, 2019). "The presence of a dominant neoplastic clone with FIP1L1-PDGFRA rearrangement was suspected on the basis of sudden onset of peripheral and bone marrow eosinophilia and confirmed by fluorescence in situ hybridization and molecular diagnostic tests." (PMID 24669761, 2014). "In the presence of peripheral blood eosinophilia (> 1500 cells/ml), investigation of the CHIC-2 deletion and FIP1L1-PDGFRA rearrangement by means of fluorescence in situ hybridization or the reverse transcriptase polymerase chain reaction is indicated." (PMID 24141298, 2013). "The detection of FIP1L1-PDGFRA rearrangement in the second patient, directly after the estimation of eosinophilia, resulted in the early diagnosis of CEL, with a profound impact on the patient's clinical course and outcome." (PMID 19187542, 2009). "In our cohort, the prevalence of FIP1L1-PDGFRA rearrangement was 13.3% in the total analysed group and 40% among patients with primary eosinophilia." (PMID 19187542, 2009).
eosinophilia (continued). "Still, the prior exclusion of FIP1L1::PDGFRA positive cases by RT‐PCR might be advised to reduce costs and to reserve the analysis for patients with persisting, unexplained eosinophilia and related organ damage." (PMID 40533930, 2025). "The incidence has been reported to be 0.036/100,000 for HES in the USA and 0.018/100,000 specifically diagnosed with the most prevalent primary eosinophilia, a factor interacting with PAPOLA and CPSF1-platelet-derived growth factor receptor alpha (FIP1L1-PDGFRA)-positive neoplasms, in France." (PMID 37274287, 2023). "FIP1L1::PDGFRA and ETV6::ABL1 fusion genes share striking clinical and morphological similarities including male predominance, the relative frequency of eosinophilia and monocytosis, the median absolute number of eosinophils, and presentation or progression to BP including EMD." (PMID 37454239, 2023). "If the patient did not improve and peripheral eosinophilia still persists, we would have planed to perform a bone marrow biopsy and obtain FIP1L1-PDGFR alpha to evaluate bone marrow diseases such as myeloproliferative neoplasms and hypereosinophilic syndrome." (PMID 27520469, 2016). "Since our patient did not have peripheral eosinophilia, there was no indication to order specific testing for the FIP1L1-PDGFRA rearrangement." (PMID 26457233, 2015). "All patients with primary eosinophilia negative for the FIP1L1-PDGFRA rearrangement, displayed eosinophilia for more than 6 months (mean: 7 months, range: 6–8)." (PMID 19187542, 2009). "If these translocations are negative, there is peripheral eosinophilia, or there is a history of leukocytosis with eosinophilia, we recommend FISH for ETV6-ABL1, FIP1L1-PDGFRA, PDGFRB, or FGFR1 rearrangements." (PMID 38337573, 2024). "The FIP1L1-PDGFRA primary myeloid neoplasm is more prevalent in male adults, but otherwise, iHES and clonal primary eosinophilia are overall not gender-specific and can be diagnosed at all ages." (PMID 37274287, 2023). "A case series from Germany described five patients with FIP1L1- PDGFRA who presented with AML and eosinophilia, but no history of antecedent myeloid malignancy was reported for any of the patients." (PMID 24669761, 2014). "Regardless of the presence or absence of FIP1L1-PDGFRA or C-KIT-D816V, patients with SM may present with eosinophilia." (PMID 19187542, 2009). "In 81/135 (60%) evaluable patients, hypereosinophilia (>1.5 × 109/l) was observed in 40/44 (91%) FIP1L1::PDGFRA and 7/7 (100%) ETV6::ABL1 positive patients but only in 13/30 (43%) patients with PDGFRB, FGFR1, and JAK2 fusion genes while 9/30 (30%) patients had no eosinophilia." (PMID 37454239, 2023).
chronic eosinophilic leukemia (26 papers, 2007 to 2025). "In summary, we present a 71-year-old man presenting with nonspecific symptoms of cough, weight loss, and night sweats who was ultimately diagnosed with FIP1L1-PDGFRα mutation-positive chronic eosinophilic leukemia." (PMID 40144421, 2025). "Factor interacting with PAPOLA and CPSF1 (FIP1L1), fused with platelet-derived growth factor receptor α (PDGFRα), has been linked to several hematologic malignancies (hypereosinophilic syndrome, chronic eosinophilic leukemia, systemic mastocytosis)." (PMID 35494081, 2022). "Imatinib turned out to block PDGF receptor at low dose, exerting a pharmacological effect for BCR-ABL positive CML and FIP1L1-PDGFRA mutated eosinophilic leukemia patients, suggesting PDGF signaling as an activated effector in hematological malignancies." (PMID 32571260, 2020). "The CML blast crisis cell line K562, harboring a BCR-ABL1 fusion mutation, and the eosinophilic leukemia cell line EOL-1 (harboring a FIP1L1-PDGFRA mutation), were treated with crenolanib." (PMID 29137311, 2017). "FIP1L1- PDGFRA rearrangements are often associated with chronic eosinophilic leukemia and hypereosinophilic syndromes as well as systemic mastocytosis." (PMID 24669761, 2014). "The FIP1L1/PDGFRA fusion is a hallmark of chronic eosinophilic leukemia and has been studied extensively in EOL-1 cells, but other cell line models are lacking." (PMID 23637631, 2013). "T674I FIP1L1-PDGFRα in a subset of chronic eosinophilic leukemia (CEL) is a gatekeeper mutation that is resistant to many tyrosine kinase inhibitors (TKIs) (e.g., imatinib, nilotinib and dasatinib), similar to T315I Bcr-Abl." (PMID 24472312, 2014). "Fluorescence in situ hybridization (FISH) and cytogenetic testing confirmed that the patient had FIP1L1-PDGFRα-positive chronic eosinophilic leukemia." (PMID 40144421, 2025). "Among the causes of reactive HE/HES, recent onset of HE/HES should primarily suggest helminthiasis or drug hypersensitivity, as detailed in “Management of FIP1L1::PDGFRA–positive chronic eosinophilic leukemia” section." (PMID 37122022, 2023). "In conclusion, this study demonstrates that S100A8 and S100A9 trigger apoptosis of chronic eosinophilic leukemia by induction of intrinsic apoptosis and suppression of FIP1L1-PDGFRα+-mediated proliferation." (PMID 32903598, 2020). "FIP1L1/PDGFRA (F/P) rearrangement is the most common molecular abnormality in chronic eosinophilic leukemia (CEL)." (PMID 27120808, 2016). "The FIP1L1/PDGFRA (F/P) fusion gene is the most common clonal genetic abnormality of chronic eosinophilic leukemia (CEL)." (PMID 27120808, 2016). "During the past decade, the tyrosine kinase inhibitor (TKI) imatinib has been successfully used for the treatment of patients with BCR/ABL1+ chronic myeloid leukemia (CML) and for the treatment of FIP1L1/PDGFRA+ chronic eosinophilic leukemia (CEL)." (PMID 25605011, 2015). "Many of these breakpoints corresponded to known gene fusions, including BCR/ABL1 in CML, FIP1L1/PDGFRA in eosinophilic leukemia, and NPM1/ALK in anaplastic large cell lymphoma (ALCL)." (PMID 23637631, 2013). "The diagnosis of chronic eosinophilic leukemia was ruled out due to the negative FIP1L1-PDGFRA mutation test results." (PMID 39996194, 2025). "The FIP1(14.7K-interacting protein 1)-like-1–platelet-derived growth factor receptor-α (FIP1L1-PDGFRA) fusion gene is a barometer distinguishing chronic eosinophilic leukemia (CEL) and other eosinophilic disorders, such as reactive eosinophilia (RE) and hypereosinophilic syndrome (HES)." (PMID 32903598, 2020). "FIP1L1-PDGFRA is a recurrent fusion in chronic eosinophilic leukemia." (PMID 30474028, 2018). "FIP1L1-PDGFRα-positive chronic eosinophilic leukemia (CEL) is a rare subtype of myeloproliferative neoplasm characterized by organ damage caused by eosinophilic granules containing cytokines and humoral factors." (PMID 40144421, 2025).
chronic eosinophilic leukemia (continued). "Chronic eosinophilic leukemia (CEL) is a rare hematological malignancy having elevated levels of eosinophils and characterized by the presence of the FIP1L1-PDGFRA fusion gene." (PMID 32903598, 2020). "The most sensitive cell line was the chronic eosinophilic leukemia cell line EoL-1 (IC50 = 59 nmol/L), expressing a fusion gene of Factor Interacting with PAPOLA and CPSF1 (FIP1L1) and platelet-derived growth factor receptor α (PDGFRα)." (PMID 41199836, 2025). "Further testing, such as FISH and cytogenetic testing, confirmed the diagnosis of chronic eosinophilic leukemia with a CHIC2 deletion and FIP1L1-PDGFRα translocation, showing 60% of abnormal cells." (PMID 40144421, 2025). "Fluorescence in situ hybridization revealed the FIP1L1-PDGFRA gene fusion and bone marrow analysis confirmed a diagnosis of chronic eosinophilic leukemia." (PMID 33585139, 2021). "Later, imatinib was also found to block the kinase activity of FIP1L1-PDGFRA, the major driver of oncogenesis in chronic eosinophilic leukemia (CEL) and in a subset of related myeloid malignancies." (PMID 30759825, 2019).